ACTL10 (actin like 10)
Synonyms: C20orf134; dJ63M2.2
Tractability: Antibody: the Human Protein Atlas places it where antibodies can reach.
Gene: Protein-coding gene on chromosome 20 (33,666,943 to 33,668,525, forward strand). Ensembl gene ENSG00000288649.
Subcellular location (Human Protein Atlas): Plasma membrane; Vesicles; Nucleoplasm
Gene Ontology:
Molecular function: structural constituent of cytoskeleton
Biological process: cytoskeleton organization
Cellular component: actin cytoskeleton
Genetic constraint (gnomAD): Loss-of-function variants: 5 observed, 2.86 expected, observed/expected ratio (o/e) 1.75, 90% interval 0.77 to 1.95. That is too few expected variants to judge how well the gene tolerates losing a copy. Missense variants: 413 observed, 338.25 expected, observed/expected ratio (o/e) 1.22, 90% interval 1.13 to 1.33. Synonymous variants: 180 observed, 156.92 expected, observed/expected ratio (o/e) 1.15, 90% interval 1.01 to 1.3.
Homologues: Orthologues: chimpanzee ACTL10 (100% identical), pig ACTL10 (82% identical), rat Actl10 (78% identical), mouse Actl10 (78% identical). Paralogues in human: ACTL7A (36% identical), ACTBL2 (34% identical), ACTL7B (34% identical), ACTB (34% identical), ACTG1 (34% identical), ACTR1B (34% identical), ACTA1 (33% identical), ACTA2 (33% identical), ACTC1 (33% identical), ACTG2 (33% identical), ACTL9 (33% identical), ACTR1A (32% identical), and 14 more.
Diseases named in the same sentence as ACTL10 in open-access papers:
ACTL10 is named in the same sentence as 4 diseases in open-access papers, as found by Europe PMC text mining. Sharing a sentence is not in itself a finding about the gene and the disease. The quoted sentences say what the papers report.
acute myeloid leukemia (1 paper, 2020). Acute myeloid leukemia (AML) is a group of neoplasms arising from precursor cells committed to the myeloid cell-line differentiation. "Thus, the present study aimed to determine the association between ACTL10 expression levels, DNA methylation levels and the clinical prognosis in cytogenic normal acute myeloid leukemia (CN-AML)." (PMID 32742462, 2020).
leukemia (1 paper, 2020). A malignant (clonal) hematologic disorder, involving hematopoietic stem cells and characterized by the presence of primitive or atypical myeloid or lymphoid cells in the bone marrow and the blood. "ACTL10 is a member of the actin family, which is closely associated with the pathogenesis of leukemia through regulating proliferation, differentiation and the migration of hematopoietic stem/hematopoietic progenitor cells; however, the clinical association between ACTL10 and CN-AML remains unknown." (PMID 32742462, 2020). "ACTL10 is a member of the actin family; however, despite previous studies suggesting that certain proteins in this family may be related to the pathogenesis of leukemia, to the best of our knowledge, no studies to date have demonstrated any association between ACTAL10 and leukemia." (PMID 32742462, 2020).
infection (1 paper, 2020). The state of being infected such as from the introduction of a foreign agent such as serum, vaccine, antigenic substance or organism. "Cytoskeleton-related genes such as ACTL10 and Cdc42 were overexpressed in basolateral infection compared to apical infection." (PMID 32872518, 2020).
ACTL10 also shares sentences with these, for which no sentence is quoted: myeloid leukemia (1 paper).